TLR5 (toll like receptor 5)
Diseases named in the same sentence as TLR5 in open-access papers (continued):
Sharing a sentence is not in itself a finding about the gene and the disease.
Insulin resistance (23 papers, 2011 to 2025). Increased resistance towards insulin, that is, diminished effectiveness of insulin in reducing blood glucose levels. "TLR5 is important for metabolism since its deficiency can lead to hyperlipidemia, insulin resistance, weight gain, and changes in gut microbiota." (PMID 39273662, 2024). "The gut microbiome seems to regulate TLR-mediated insulin resistance as experimental studies in mice deficient-TLR5 developed metabolic syndrome and insulin resistance due to dysregulation of IL-1β signaling." (PMID 33802371, 2021). "In the current study, a second mouse line with TLR5 gene deficiency (TLR5KO2) was studied with the objective to understand the mechanisms by which TLR5 deficiency can cause host insulin resistance." (PMID 26950299, 2016). "Examining the gut microbiome composition in TLR5-deficient mice reveals that it was altered in such a way that it induced low-level inflammatory signaling, this in turn, attenuated insulin signaling to promote insulin resistance and hyperphagia." (PMID 31952471, 2020). "Both TLR4- and TLR9-deficient mice are protected from high-fat diet-induced inflammation and insulin resistance, while mice deficient in TLR5 develop all features of metabolic syndrome including hyperphagia, obesity, insulin resistance, pancreatic inflammation, and hepatic steatosis." (PMID 27247565, 2016). "Conversely, TLR5 knockouts in mice have been shown to induce insulin resistance, hyperphagia, and many other symptoms characteristic of metabolic disorders." (PMID 31952471, 2020). "TLR5 KO leads to hyperlipidemia, hypertension, insulin resistance accompanied by microbial composition shift and is transferrable to WT GF mice upon FMT." (PMID 31258528, 2019). "Toll-like receptor 5 (TLR5) is expressed in the gut mucosa and it was demonstrated that TLR5−/− mice exhibited hyperphagia and developed metabolic disturbances, including insulin resistance, and increased adiposity." (PMID 22509382, 2012). "Moreover, the alteration of the TLR5 expression was described in individuals with insulin resistance, which is a very prevalent condition in subjects with schizophrenia." (PMID 32854231, 2020). "In addition, the insulin resistance of TLR5−/− mice is not entirely dependent on increased food consumption or adiposity seeing that the lean TLR5−/− mice after 12 weeks of food restriction regimen still exhibited a decreased response to exogenous insulin." (PMID 26681840, 2015). "Mice lacking Toll-like receptor 5 (TLR5), which is important in immune system recognition of bacterial antigens in the colon, are hyperphagic with increased food consumption resulting in hyperlipidemia, hypertension, insulin resistance, and increased adipocity." (PMID 22042266, 2012). "Furthermore, mice lacking Toll-like receptor 5 (TLR5), on a mixed C57BL/6J and C57BL/6N genetic background, develop insulin resistance and increased adiposity." (PMID 26681840, 2015).
gastric cancer (21 papers, 2013 to 2025). A primary or metastatic malignant neoplasm involving the stomach. "A more recent study, which included 1300 cases of gastric cancer and 1300 healthy controls from China, identified that two other polymorphisms in TLR5, namely, rs1640827 and rs17163737, were associated with H. pylori infection and, subsequently, with a high risk for gastric carcinoma." (PMID 30863783, 2019). "Further, results derived from other populations, and association studies between the TLR5 polymorphisms and expression of inflammatory cytokines in the gastric cancer tissues are needed to better understand the complicated mechanisms underlying the modifying effect of the TLR5 gene." (PMID 28404962, 2017). "The polymorphisms rs1640827 and rs17163737 of TLR5 enhance Helicobacter pylori susceptibility, elevating the risk of gastric cancer (GC)." (PMID 40727252, 2025). "In gastric cancers whose epithelial cells stain strongly for TLR5 show a 5-year disease-specific survival of 53% versus 38% for TLR5-low tumors (p = 0.014)." (PMID 41465346, 2025). "On the contrary, TLR2 and TLR5 signal pathways can enhance the proliferation and survival of gastric cancer cells and promote tumor migration." (PMID 38063246, 2023). "Some studies assessing the role of polymorphisms in TLR2, TLR4, TLR5, NOD1 and NOD2 in gastric cancer have been published." (PMID 33879265, 2021). "The aim of this study was to assess if polymorphisms of TLR2, TLR4, TLR5, NOD1 and NOD2 genes are associated with gastric cancer, in particular in individuals infected with H. pylori." (PMID 33879265, 2021). "The aim of our study was to assess the association of common polymorphisms in TLR2, TLR4, TLR5, NOD1 and NOD2 with gastric cancer in H. pylori infected subjects." (PMID 33879265, 2021). "Our results differ through the application of immunohistochemistry on surgical patient samples, where we show that the prognosis amongst gastric cancer patients with a high TLR5 expression is better than amongst those with a low tumour tissue expression." (PMID 31467388, 2019). "Subsequent TLR5 antagonism appeared to cancel the effect, suggesting that TLR5 signalling clearly contributes to the proliferation of gastric cancer cells." (PMID 31467388, 2019). "The five-year disease-specific survival amongst gastric cancer patients with a high TLR5 expression was 53.4% (95% CI 43.4–63.4), compared to 37.6% (95% CI 30.0–45.2) among those with a low TLR5 expression (p = 0.014)." (PMID 31467388, 2019). "In this study, we found that in 85As2 cells, which were established from MKN45cl85 human gastric cancer cells, the TLR5 signaling pathway was activated with increased IRAK-1/4 expression compared to in the parent cell line." (PMID 30410674, 2018). "The current study systematically explored the function of genetic variations of TLR5, and their interaction with Helicobacter pylori infection among carcinogenesis of gastric cancer in a Chinese population, using a large scale, case-control study." (PMID 28404962, 2017). "In current study, we systematically evaluated genetic variations of TLR5, and their interaction with Helicobacter pylori infection among carcinogenesis of gastric cancer, using a large case-controls study among Chinese population." (PMID 28404962, 2017). "Here, we systematically evaluated the function of genetic variations of TLR5, and their interaction with Helicobacter pylori infection among carcinogenesis of gastric cancer in a Chinese population." (PMID 28404962, 2017). "It has also been shown that TLR5 is overexpressed in gastric carcinoma cells, and activation of TLR5 by flagellin provokes potent antitumor activity and thus inhibits the growth of colon tumors in vivo." (PMID 24932259, 2014). "It was reported that stimulation of TLR5 using flagellin resulted in IL-8 production in epithelial cells and gastric cancer cells, increasing the proliferation of these cells, and the production of IFN-γ." (PMID 23844139, 2013).
gastric cancer (continued). "However, in another study, the expression of TLR1, TLR2, TLR4, TLR5 and TLR6 was associated with survival in gastric cancer, and only high cytoplasmic TLR2 expression was shown to be significantly associated with a poorer 5-year survival." (PMID 40362298, 2025). "TLR5 has been proposed to activate nuclear factor-κB (NF-κB) in gastric cancer." (PMID 34503162, 2021). "In addition, TLR5 activation by flagellin, the major structural protein in bacterial flagellum, increases the proliferation of gastric cancer cells." (PMID 31467388, 2019). "In addition, we found that a high expression of TLR1, TLR2, TLR4, TLR5, TLR7, and TLR9 associated with an intestinal-type gastric cancer and with a high expression of all other TLRs." (PMID 31467388, 2019). "To conclude, in this study we show, for the first time, that a high TLR5 tissue expression may identify gastric cancer patients with a better prognosis, particularly amongst those with a stage II disease or an intestinal-type cancer." (PMID 31467388, 2019). "Therefore, in this study, we aimed to explore the tissue expression of TLR1, TLR2, TLR4, TLR5, TLR7, and TLR9 as potential prognostic biomarkers in gastric cancer patients, and to examine their associations with several clinicopathological variables." (PMID 31467388, 2019). "Additionally, the authors encountered also a significant correlation between TLR5 rs5744174 and gastric cancer." (PMID 30863783, 2019). "In this study we show, for the first time, that a high TLR5 tissue expression may identify gastric cancer patients with a better prognosis, particularly among those with a stage II disease or an intestinal-type cancer." (PMID 31467388, 2019). "TLR5 is capable of recognizing bacterial flagellin, and it is hypothesized that H. pylori recognition by TLR5 could lead to the activation of nuclear factor-κB (NF-κB) in gastric cancer." (PMID 32023907, 2020). "In this study, we show for the first time that a high TLR5 tissue expression may identify gastric cancer patients with a favourable outcome, particularly amongst those with stage II disease, an intestinal-type cancer, without distant metastases or a younger age." (PMID 31467388, 2019). "TLR5 exacerbates airway inflammation and asthma symptoms, while RAB13 serves as a novel prognostic marker in gastric cancer." (PMID 39655195, 2024). "Increasing expression of TLR2, TLR4, TLR5, and TLR9 in gastric epithelia of children' gastritis; TLR4, TLR5, and TLR9 in adults' gastritis; TLR2, TLR4, and TLR5 in gastric dysplasia; and TLR4, TLR5, and TLR9 in gastric cancer (GC) is found." (PMID 35300405, 2022). "Recently, the tissue expressions of TLR1, TLR2, TLR4, TLR5, TLR7 and TLR9 as potential prognostic biomarkers in gastric cancer were reported, showing a positive correlation between each other and a high expression of each studied TLR in tumors with an intestinal-type histology." (PMID 40362298, 2025). "In gastric cancer TLR4 and TLR5 activation induced cancer cell survival." (PMID 38709790, 2024). "Thus, we aimed to evaluate the tissue expressions of TLR1, TLR2, TLR4, TLR5, TLR7, and TLR9 as potential prognostic biomarkers in gastric cancer." (PMID 31467388, 2019). "In addition to TLR5, TLR1, TLR2, TLR4, TLR7, and TLR9 were also expressed in gastric cancer tissues, yet their expression levels did not function as prognostic biomarkers across the entire patient cohort." (PMID 31467388, 2019).
viral infection (20 papers, 2013 to 2024). "There is some evidence that polymorphisms in the TLR5 gene are associated with bacterial infections, but their role in viral infections is less studied." (PMID 30623075, 2018). "Thus, if TLR5 activity is maintained flagellin may enhances susceptibility to viral infection in individuals with a diminished anti-viral-associated TLR activity related to immune senescence." (PMID 31133714, 2019). "As such, vaccines demonstrating binding affinity toward TLR5 are likely to elicit potent immune responses against viral infections." (PMID 38400123, 2024). "Though TLR5 is widely reported to be engaged in flagellin recognition, its role in viral infection remains unknown." (PMID 32213866, 2020). "Reporter assays have also linked missense SNPs that are located within TLR2 and TLR5 to a differential reactivity to Salmonella enterica and within TLR3 to different responses to stimulation by poly(A:C), a synthetic acid that emulates viral infection." (PMID 27036198, 2016). "Moreover, mice maintained with a microbiota but lacking TLR5 also exhibited reduced responsiveness to this vaccine thus together suggesting a reliance upon TLR5 by microbiota derived flagellin to maintain the immune system in a state ready to quickly respond vaccines and presumably viral infections." (PMID 29534424, 2018). "TLR5 is commonly utilized in fish vaccine construction, while TLR3 plays a significant role in viral infections." (PMID 38782944, 2024). "In this study, we focused on TLR1, TLR2, TLR4, TLR5, TLR6 and TLR9 expression fold changes in two genital epithelial cells (HEC-1-A and VK2) after viral infection." (PMID 30419930, 2018). "TLR4, TLR5, TLR15, and TLR16 belong to the TLR family and are involved in sensing and initiating immune responses to viral infection." (PMID 24168272, 2013). "Additionally, flagellin activates IL-22 and IL-18 activation through TLR5/NLRC4, driving IL-18-induced apoptosis of viral infection as well as IL-22-induced proliferation, thereby inhibiting viral infection." (PMID 35216425, 2022). "Regardless of this, known ligands for TLR3 and TLR5, widely used to mimic bacterial and viral infections, respectively, elicit clear changes in gene expression and the production of cyto/chemokines by individual human embryos." (PMID 34517414, 2021). "Where several studies describe the role of TLR4 during viral infection, as TLR4 is upregulated in response to CVB3 inoculation on the plasma membrane and contributes to its pathogenesis, the contribution of especially TLR3 and TLR5 is less founded." (PMID 27878326, 2017). "Considering TLR5 plays a feeble role in virus infection, it was not discussed in the present study." (PMID 28747721, 2017). "Besides, selected probiotic strains also showed no NF‐κB activity via TLR5 and TLR9, thus excluding other TLR signalling, since lactic acid bacteria and bifidobacteria do not possess LPS (TLR4 signalization) and the remaining TLRs are associated mainly with viral infections." (PMID 32945079, 2021).
inflammatory bowel disease (19 papers, 2010 to 2025). A spectrum of small and large bowel inflammatory diseases of unknown etiology. "A minor allele in TLR5 (rs5744174) has previously been associated with response to ustekinumab in psoriasis and TNFi in rheumatoid arthritis and inflammatory bowel diseases." (PMID 41009564, 2025). "Single nucleotide polymorphisms (SNP) in the TLR5 gene have been associated with human inflammatory bowel disease (IBD) and animal models of this disease." (PMID 22279566, 2012). "TLR5 G22A, TLR5 C100T and TLR5 T1844C genotype association with inflammatory bowel disease in German shepherd dogs." (PMID 21203467, 2010). "Also, according to this latest study, the A1571T and G1807A SNPs, in combination with the TLR-5 SNP G22A, showed a significant association with inflammatory bowel disease (IBD)." (PMID 40725420, 2025). "So far, polymorphisms in TLR4 and TLR5 have been associated with Inflammatory Bowel disease (IBD) in German Shepherd dogs (GSD), but only protective SNPs from TLR5 have been associated with IBD in other 38 dog breeds There is therefore great interest in the characterization of canine TLRs." (PMID 26401328, 2014). "Several SNPs were identified in the TLR-4 and TLR-5 genes in the German Shepherd breed that are associated with inflammatory bowel disease (IBD)." (PMID 40725420, 2025). "While the precise mechanism by which loss of TLR5 and MUC2 promotes inflammatory bowel diseases remains under investigation." (PMID 35571126, 2022). "The TLR5*B allele encodes for one of the two variants at the amino acid level (the alternative being TLR5*A), characterized by 4 SNPs including the T8A, associated with IBD (inflammatory bowel disease)." (PMID 33167491, 2020). "In inflammation TRIB2 has been described as a regulator of NF-κB activity associated with inflammatory bowel disease (IBD), and TRIB2 inhibits TLR5-mediated activation of NF-κB." (PMID 34070799, 2021). "Mice lacking TLR5 develop features resembling inflammatory bowel disease (IBD), including enhanced susceptibility to colitis and chronic mucosal immune activation driven by overgrowth of flagellated pathobionts." (PMID 41369391, 2025). "In inflammatory bowel disease, the active inflamed tissue exhibits reduced Trib2 (TRIB2) expression, and Trib2 inhibits NF-κB activation mediated by Toll-like receptor 5 (TLR5)." (PMID 36979341, 2023). "Indeed, human IECs constitutively express TLR3, TLR5, TLR9, NOD1, NOD2 and low levels of TLR2 and TLR4, where TLR4 is increased in inflammatory bowel disease (IBD) IECSs and intestinal macrophages." (PMID 36296363, 2022). "Colonic IECs from patients with inflammatory bowel disease (IBD) have higher expression levels of TLR4 in particular, as well as lower levels of TLR2 and TLR5." (PMID 29438282, 2018). "Cario and Podolsky analysed TLR2, TLR3, TLR4, and TLR5 protein levels in colonic biopsies and found that TLR4 protein levels were higher in both the inflamed and the noninflamed colonic mucosa of patients with inflammatory bowel disease compared to controls." (PMID 28246611, 2017).
Crohn disease (16 papers, 2010 to 2025). A gastrointestinal disorder characterized by chronic inflammation involving all layers of the intestinal wall, noncaseating granulomas affecting the intestinal wall and regional lymph nodes, and transmural fibrosis. "Since MDP-induced CCL20 expression via the TLR5/NOD2 response loop is known to be influenced by Crohn’s disease-specific NOD2 mutations, we speculated that NOD2 mutations might impact systemic CCL20 levels and explain this specificity." (PMID 40542081, 2025). "Association between SNPs across the TLR5 gene and Crohn's disease." (PMID 23593463, 2013). "Association between haplotypes comprising TLR5 SNPs and Crohn's disease." (PMID 23593463, 2013). "In addition, a dominant-negative TLR5 polymorphism termed TLR5-stop protected people of Jewish ethnicity against Crohn's disease (CD)." (PMID 21203467, 2010). "Our findings significantly contribute to the understanding of the mechanism of TLR5 activation, which plays an important role in host defense against several pathogens, but also in several diseases, such as Crohn’s disease, cystic fibrosis and rheumatoid arthritis." (PMID 28827825, 2017). "The aim of our studies was to investigate the expression of Toll-like receptor (TLR)-2 and TLR-4 (and in some studies TLR-5) in myofibroblasts and small and large intestinal crypt epithelial cells from control patients and those affected by Crohn's disease and ulcerative colitis." (PMID 24828022, 2014). "Although numerous studies have implicated TLR5, or its ligands, bacterial flagellins, in the pathogenesis of Crohn's disease (CD), genome-wide association studies (GWAS) have not reported associations with the TLR5 gene." (PMID 23593463, 2013). "However, with the inflammatory conditions characteristic of Crohn’s disease, Paneth cells are likely under stress that results in impaired function, which could be further exacerbated by excessive TLR5 signaling due to elevated number of flagella." (PMID 35401545, 2022). "For example, TLR3 is downregulated in active Crohn's disease but not in ulcerative colitis and TLR5 is upregulated in both forms of IBD." (PMID 26090491, 2015).